RN7SL387P (RNA, 7SL, cytoplasmic 387, pseudogene)
Gene: Miscellaneous RNA gene on chromosome 12 (110,625,645 to 110,625,917, reverse strand). Ensembl gene ENSG00000263537.
Homologues: Orthologues: chimpanzee Metazoa_SRP (97% identical). Paralogues in human: RN7SL718P (85% identical), RN7SL602P (83% identical), Metazoa_SRP (83% identical), RN7SL525P (82% identical), Metazoa_SRP (82% identical), Metazoa_SRP (81% identical), Metazoa_SRP (80% identical), RN7SL121P (79% identical), Metazoa_SRP (79% identical), RN7SL524P (78% identical), Metazoa_SRP (78% identical), RN7SL353P (77% identical), and 711 more.